BIRC2 (baculoviral IAP repeat containing 2)
Diseases named in the same sentence as BIRC2 in open-access papers (continued):
Sharing a sentence is not in itself a finding about the gene and the disease.
oral cancer (4 papers, 2016 to 2025). "Here, we validate the amplifications of 11q13.3 and 11q22.1-q22.2 in OSCC and evaluated the expression of BIRC2 and BIRC3 with respect to lymph node metastasis and poor survival in oral cancer patients." (PMID 29167558, 2017).
rheumatoid arthritis (4 papers, 2023 to 2025). A chronic, systemic autoimmune disorder characterized by inflammation in the synovial membranes and articular surfaces. "The findings indicated that BIRC2 exhibited significant differential expression when comparing rheumatoid arthritis (RA) samples to normal controls (NC)." (PMID 40034747, 2025). "Baculoviral IAP repeat‐containing 2 (BIRC2) knockdown could attenuate the progression of rheumatoid arthritis by inhibiting inflammation, oxidative stress, and necroptosis." (PMID 37904685, 2023). "In addition, gene expression analysis revealed a significant upregulation of BIRC2 expression in individuals with rheumatoid arthritis, with cIAP1 being a central protein identified in protein-protein interaction networks linked to rheumatoid arthritis." (PMID 37090690, 2023). "Combining anti-tumor necrosis factor therapy with cIAP1/2 inhibitors by blocking the BIRC2/BIRC3-mediated apoptotic pathway has the potential to improve therapeutic efficacy and effectively reduce symptoms and disease progression in rheumatoid arthritis." (PMID 39301019, 2024).
COVID-19 (3 papers, 2021 to 2025). A disease caused by infection with severe acute respiratory syndrome coronavirus 2. "The respective APNet bipartite graph contained a large cluster (IL10RA, ACTN4, ITGB2, IL2RB, BIRC2, ITGAM, HMOX1, TIMP1) linked with established COVID-19 inflammatory and immune signalling cascades." (PMID 39921901, 2025).
prostate tumor (3 papers, 2010 to 2016). "AMPA treatment decreased expression of BIRC2 and activated caspase 3, leading to increased apoptosis in the prostate tumors." (PMID 26840261, 2016).
Cerebral ischemia (2 papers, 2021 to 2023). Restriction of arterial blood supply to the brain associated with insufficient oxygenation to support the metabolic requirements of the tissue. "Currently, the abnormal expression of BIRC2 has been discovered in multiple diseases, and BIRC2 is demonstrated to regulate the progression of various diseases, including cancers, infection, and cerebral ischemia." (PMID 37904685, 2023).
HIV-1 infection (2 papers, 2011 to 2025). The type species of lentivirus and the etiologic agent of acquired immunodeficiency syndrome (AIDS). "In addition, a previous study implicated the BIRC2 and BIRC3 protein products cIAP1 and cIAP3, respectively, in protecting macrophages from Vpr-induced cell death during HIV-1 infection." (PMID 40901928, 2025). "Three of these genes baculoviral IAP repeat containing 2 (Birc2), Myc and FN1 are strongly down-regulated, and CDKN2A, CDKN2B and BRAC1 are moderately down-regulated during acute HIV-1 infection." (PMID 21533265, 2011).
metastatic tumor (2 papers, 2007 to 2015). "Interestingly, several genes in this cluster or their homologs involved in angiogenesis and inhibition of apoptosis have previously been associated with metastatic tumor progression in murine SCC or human HNSCC (IL6, IL8, YAP1, and BIRC2), and shown to be regulated by NF-κB." (PMID 17498291, 2007).
Barrett esophagus (1 paper, 2025). Esophageal lesion lined with columnar metaplastic epithelium which is flat or villiform. "Research focused on Barrett’s esophagus and esophageal adenocarcinoma have also suggested that BIRC2, BIRC3, MMP12, MYC, PVT1, and YAP1 may be ecDNA-related oncogenes." (PMID 40569942, 2025).
cholesteatoma (1 paper, 2012). A pathologic process characterized by the proliferation of keratinizing squamous epithelium resulting in the accumulation of keratin and cells in the middle ear and/or mastoid. "A down-regulation of cIAP1 (BIRC2) was observed, whereas p65 (RELA), cFlip (CFLAR) and Bcl-2 show similar expression levels in cholesteatoma and external auditory skin samples." (PMID 23285167, 2012).
endometriosis (1 paper, 2022). The growth of functional endometrial tissue in anatomic sites outside the uterine body. "Increased expression of BIRC2, BIRC3, BIRC4, and BIRC5 is associated with endometriosis, and tumor necrosis factor-α increases BIRC3 expression in endometrial stromal cells in vitro." (PMID 34530503, 2022).
endothelial dysfunction (1 paper, 2022). In vascular diseases, endothelial dysfunction is a systemic pathological state of the endothelium (the inner lining of blood vessels) and can be broadly defined as an imbalance between vasodilating and vasoconstricting substances produced by (or acting on) the endothelium. "In these conditions of muscular and/or endothelial dysfunctions likely triggering apoptotic events, it could be hypothesized the role of the hub gene BIRC2 in contrasting the ER-stress apoptosis by acting against the altered cellular functionality induced by the ER stress." (PMID 35874513, 2022).
Ewing sarcoma (1 paper, 2011). A small round cell tumor that lacks morphologic, immunohistochemical, and electron microscopic evidence of neuroectodermal differentiation. "We also found downregulation of the anti-apoptotic BIRC-2 (cIAP1) and BIRC-3 (cIAP2) proteins in Ewing’s sarcoma SK-N-MC xenografts." (PMID 21822457, 2011).
gout (1 paper, 2021). A condition characterized by painful swelling of the joints, which is caused by deposition of urate crystals. "Gene is downregulated in association with promoter hypermethylation, Here, hypermethylation of BIRC2 likely suppressed BIRC2 expression and increased IL-1β production, exacerbating gout." (PMID 33493135, 2021). "The final nine surviving monocyte-specific differentially methylated CpG sites were mapped to eight genes (PRKCZ, CIDEC, VDAC1, CPT1A, BIRC2, BRCA1, STK11, and NLRP12) that have not previously been studied in the field of gout genetics." (PMID 33493135, 2021).
mastitis (1 paper, 2025). Inflammation of breast tissue during lactation or postpartum due to an obstructed duct or infection. "Transcriptome analysis have shown that BIRC2 and BIRC3 are upregulated in mammary glands infected with Staphylococcus aureus response, suggesting their role in immune response to mastitis." (PMID 41252605, 2025).
peripheral nerve injury (1 paper, 2025). Injury to a peripheral nerve. "Furthermore, research on peripheral nerve injury revealed that TNFRSF1A, BIRC2, and BIRC3 in Schwann cells (SC) assume an anti-apoptotic function by modulating NFκB signaling pathway in response to inflammatory stimuli, thereby mitigating peripheral nerve damage." (PMID 40308566, 2025).
rectal adenocarcinoma (1 paper, 2023). "Out of all 155 target genes, only higher BIRC2 and FGF16 transcript levels were significantly associated with increased and decreased overall survival, respectively, in rectal adenocarcinoma." (PMID 37345032, 2023).
small cell lung carcinoma (1 paper, 2020). Small cell lung cancer (SCLC) is a highly aggressive malignant neoplasm, accounting for 10-15% of lung cancer cases, characterized byrapid growth, and early metastasis. "In the Small Cell Lung Cancer Signaling pathway, the molecules BIRC2, BCL2L1, and TRAF, which were commonly upregulated at 6, 12, and 24 h, were associated with the inhibition of apoptosis." (PMID 33520738, 2020).
cancer (178 papers, 2008 to 2026). A tumor composed of atypical neoplastic, often pleomorphic cells that invade other tissues. "Our findings position the Coagulation.Sig model as a novel, comprehensive approach to personalised cancer treatment, with BIRC2 emerging as both a predictive biomarker and a potential therapeutic intervention point." (PMID 40159652, 2025). "BIRC2 has been extensively studied in cancer cells and is recognized as a negative regulator of cellular apoptosis." (PMID 40389954, 2025). "Several reports indicate that BIRC2 gene expression is upregulated in multiple types of cancers and that overexpression of BIRC2 counteracts apoptosis and increases the resistance of tumor cells to chemotherapy and immunotherapy." (PMID 36788209, 2023). "An array-based analysis revealed in the second tumor an amplicon at 5q11.2 including MAP3K1 gene and the second one at 11q22.2 containing genes: YAP1 and BIRC2/3, known for its anti-apoptosis function, allowing a comprehensive view of cancer progression." (PMID 35246108, 2022). "We identified deletion of 18q21.2 and amplification of 11q22.2 as prevailing copy-number alterations in FA HNSCCs, the latter of which was associated with strong overexpression of the cancer-related genes YAP1, BIRC2, BIRC3 (at 11q22.1-2)." (PMID 34997070, 2022). "IAP antagonists are a class of compounds developed to induce cancer cell death by blocking the caspase inhibitory function of IAPs such as X-linked IAP and BIRC2." (PMID 34681681, 2021). "XIAP and BIRC2 were found to express highly among different cancers while NAIP and BIRC3 were only selectively expressed in a few cell lines." (PMID 31964418, 2020). "The upregulation of the BIRC2 gene seen in both the RNAseq screen and the qPCR was of particular interest because the gene product BIRC2 lies at a crossroads between growth, cancer, and immunity." (PMID 27822466, 2016). "Additionally, the expression of cancer marker BIRC2/cIAP1 (p = 0.002) and autophagy marker Beclin-1 (p = 0.02) were observed in plasma-derived sEVs and PanNET tissue." (PMID 38596136, 2024). "The cancer immune suppression process is mediated by the E3 ubiquitin ligase BIRC2." (PMID 39223632, 2024). "Although loss of cIAP1 in mice has been associated with locale inflammation in lung, intestines or skin, deletion or mutation of the BIRC2/3 gene has not been associated with chronic inflammatory disease but has with cancer development." (PMID 35204822, 2022). "BIRC2/3 are anti-apoptotic proteins and promote cancer cell survival." (PMID 34150758, 2021). "Interestingly, daily oral administration of Debio 1143 in cancer patients at well-tolerated doses elicited BIRC2 target engagement in PBMCs and induced a moderate increase in cytokines and chemokines mechanistically related to NF-kB signaling." (PMID 30716099, 2019). "Up regulation of several IAPs like NAIP (BIRC1), X-linked IAP (XIAP, BIRC4), Survivin (BIRC5), c-IAP1 (BIRC2), c-IAP2 (BIRC3), Apollon (BRUCE, BIRC6), Livin/MLIAP (BIRC7) and IAP-like protein 2 (BIRC8) have been reported in several cancer cells as well as in serum from cancer patients." (PMID 29464049, 2018). "Thus, our findings suggest that AMPA decreases BIRC2 expression to activate caspase 3 and then induce apoptosis in the cancer cells." (PMID 26840261, 2016). "In addition, CCNE2, PIK3CB, ITGAV, RB1, and BIRC2 involved in cancer pathway were also affected." (PMID 28567416, 2017). "These known NF-κB target genes, such as IL6, IL8, BIRC2 (clAP-1), ICAM1, YAP1, CDKN1A (p21), CSF2, CCDN1, IL1A, IL1B, and so on, include many that have been independently confirmed to be differentially expressed and pathologically implicated in HNSCC and other cancers." (PMID 18334025, 2008). "In the cancer pathway, five genes (WNT1, DLL, TRAF1, GST, and GADD45) were upregulated, while CASP3, IKBKA, STAT5A, RPS6KA5, BIRC5, BIRC2/3, and SKP2 were downregulated." (PMID 40723320, 2025).
cancer (continued). "Total RNA-seq showed upregulation of 12 putative cancer-related genes near ISs, including MAGI1-AS1, HAS3, CASC8, BIRC2, and MMP12." (PMID 41157614, 2025). "Several genes regulated by HCQ in Ca9-22 cells have been identified as potential cancer therapy targets, including TNFRSF11B, CASP6, BIRC2, and BIRC5." (PMID 41303490, 2025). "Another five targetable gene dependencies had clinical inhibitors that have reached at least a phase II trial (BIRC2, ITGB1, MAP3K11, LDHA and PTPN1), with 3 having been applied to other cancer types (BIRC2, ITGB1, and LDHA)." (PMID 37997254, 2024). "The analysis revealed that several members of the IAP family, including NAIP, BIRC2, BIRC3, XIAP, BIRC5, BIRC6, and BIRC7, exhibited higher expression levels in multiple cancers, including HCC." (PMID 37781078, 2023). "Copy number and expression analysis revealed strong correlations for a subset of the amplified cancer-related genes, YAP1, BIRC2-3, on 11q22." (PMID 34997070, 2022). "A combination of BIRC2-inhibitor LCL161 and topotecan exerted synergistic effects on cancer cells and animal tumor models." (PMID 34681681, 2021). "The overexpression of BIRC2, regulated by Pellino-1, contributes to the oncogenesis of A549 and H1299 cells, which are both LUAD cell lines, and promotes cancer cell survival." (PMID 34925455, 2021). "As SM induce the rapid degradation of BIRC2 and XIAP in cancer cells and HIV-TCM19,24,25,29–31, we evaluated the ability of the SM LCL-161, AT-406, and birinapant to induce BIRC2 and XIAP degradation in uninfected macrophages and HIV-Mφ." (PMID 32719312, 2020). "This included genes like, PIK3R2, PIK3CA, BIRC2 and ZBTB14 with implications in cancer that were over-expressed with FC above ≥10 in OS-DW in comparison to OS-R; while, expression of WNT5A, PIK3CB, ACVR1, MAPK13 and GBX2 were significantly reduced." (PMID 31690262, 2019). "Jun, CSF2 and IL-8 showed increased expression in IMR90 cells, whereas, NFκB1, NFκBIA, FN1 (fibronectin 1), GADD45A, BIRC2, TMEPAI (prostate androgen induced RNA) and CEBPB (CCAAT/enhancer binding protein) were up regulated in cancer cells." (PMID 22321936, 2012). "NAIP, BIRC2/5, and XIAP expression were related to the individual cancer stages of HNSCC." (PMID 38364254, 2024). "The copy number derived expression of 11q22.1-2 amplification resident genes was also observed in a broader cancer context; the TCGA sporadic HNSCC copy number—expression correlation data also showed significant positive correlations, most strongly in YAP1, BIRC2 and TMEM123." (PMID 34997070, 2022). "In addition, we obtained drug screen data from the “Genomics of Drug Sensitivity in Cancer” database for two TNF pathway compounds that inhibit TRAF2 binding partners, BIRC2/BIRC3 (IAP-5620) and BIRC2 (AZD5582)." (PMID 33508232, 2021). "For example, BIRC2 was clustered with BIRC3, XIAP and BIRC6 in more than 50% of the cancers." (PMID 31964418, 2020). "In addition, extracellular matrix (ECM)–receptor interaction and focal adhesion pathways were commonly caught in both cancer types, but all the corresponding bicluster targets except two (CAV2, BIRC2) were also included in PI3K/Akt signaling pathway." (PMID 30820547, 2019). "Hence, gain of the genes in apoptosis, including the anti-apoptosis genes BIRC2, BIRC3, and ATF5, can help carcinoma cells to evade apoptosis." (PMID 19911042, 2009). "In cancer cells, BIRC2 knockdown upregulates CXCL9 expression and non-canonical NF-κB signaling." (PMID 39223632, 2024). "We chose to validate BIRC2 by qPCR because it is an upregulated member of the NOD2 pathway at a crossroads between growth, immunity, and cancer, yet BIRC2 has been reported to have no phenotype when knocked down in C. elegans." (PMID 27822466, 2016).
tumor (170 papers, 2007 to 2026). "Furthermore, BIRC2 expression was significantly associated with clinical characteristics such as clinical stage, tumour size and survival status in HCC." (PMID 38538582, 2024). "The results indicated that BIRC2 knockdown in conjunction with anti‐PD‐1 treatment significantly inhibited tumour growth and reduced tumour volume, and prolonged mouse survival." (PMID 40159652, 2025). "Recent studies have shown that BIRC2 is closely linked to the expression of the CXCL9 chemokine, which recruits T cells and NK cells, thereby modulating immune regulation within the tumor microenvironment." (PMID 39833504, 2025). "Targeted BIRC2 knockdown, when combined with anti‐PD‐1 therapy, significantly suppressed tumour growth, enhanced CD8+ T cell infiltration, and amplified IFN‐γ and TNF‐α secretion in tumour models." (PMID 40159652, 2025). "Collectively, these results demonstrate that combining BIRC2 knockdown with anti‐PD‐1 therapy boosts anti‐tumour immunity, making BIRC2 a potential therapeutic target." (PMID 40159652, 2025). "The BIRC2 gene, on the other hand, is involved in regulating inhibitors of apoptosis proteins and plays a critical role in suppressing tumor cell apoptosis and promoting immune evasion." (PMID 39833504, 2025). "Our results showed that CITED4 and BIRC2 mRNA levels were significantly elevated in tumor tissues compared to normal tissues." (PMID 40389954, 2025). "High transcription level of BIRC2 was predictive of poorer patient outcomes, as was higher cIAP1 protein expression in tumors, compared to paired non-tumor counterparts." (PMID 39578442, 2024). "The data was extracted from the TCGA database and a comparative analysis revealed that BIRC2 mRNA levels were significantly higher in tumor tissues compared to normal tissues (P = 0.0028)." (PMID 39578442, 2024). "In contrast, larger vessels from EGFR-expressing tumours were enriched for Birc2 (survivin), Socs2 (suppressor of cytokine signalling 2) and Srsf2 (serine and arginine-rich splicing factor 2)." (PMID 38570528, 2024). "Recent studies have shown that BIRC2 is responsible for the apoptotic escape and multidrug resistance of tumour cells." (PMID 38538582, 2024). "BIRC2/cIAP1 and Beclin-1 expression were determined through immunohistochemistry, where brown staining in tumor cells signified positive staining, with varying intensities measured in the tissue sections." (PMID 38596136, 2024). "In our previous work, we have identified a differential reliance on TRAF2 and BIRC2 to establish resistance to TNF in different tumor cell lines." (PMID 37398651, 2023). "BIRC2 plays an important role in tumor chemotherapy, and it can also be used as a target for tumor immunotherapy." (PMID 37781078, 2023). "The results showed that BRD7 was successfully overexpressed in xenograft tumor tissues and that the expression of BIRC2 was decreased in the BRD7 overexpression group." (PMID 36788209, 2023). "BRD7 is involved in NPC tumor development and progression as a tumor suppressor and negatively regulates the expression of BIRC2." (PMID 36788209, 2023). "Meanwhile, the expression of BRD7 and BIRC2 in xenograft tumor tissues was confirmed by Western blotting." (PMID 36788209, 2023). "Collectively, these in vivo results are consistent with the patterns observed in the in vitro experiments and further confirm that BRD7 inhibits tumor metastasis at least partially by negatively regulating BIRC2 transcriptional activity and expression." (PMID 36788209, 2023). "Overall the CRISPR data indicate that the 11q22.2 amplification residing genes YAP1, TMEM123, BIRC2-3 are essential for VU1365-T tumor cells vitality." (PMID 34997070, 2022). "A functional nuclear export signal has been identified in the CARD domain of BIRC2, and the nucleocytoplasmic redistribution of BIRC2 is observed in human monocytes as well as in tumor cells." (PMID 34887869, 2021).